TCP10L2 (t-complex 10 like 2 (pseudogene))
Synonyms: bA517H2.3
Gene: Transcribed unprocessed pseudogene on chromosome 6 (167,172,145 to 167,196,679, forward strand). Ensembl gene ENSG00000166984.
Genetic constraint (gnomAD): Loss-of-function variants: 7 observed, 19.59 expected, observed/expected ratio (o/e) 0.36, 90% interval 0.2 to 0.67. The synonymous counts are far from expectation, so gnomAD's model fits this gene poorly and the ratio says little. Missense variants: 146 observed, 244 expected, observed/expected ratio (o/e) 0.6, 90% interval 0.52 to 0.69. Synonymous variants: 64 observed, 92.39 expected, observed/expected ratio (o/e) 0.69, 90% interval 0.56 to 0.85.
Diseases named in the same sentence as TCP10L2 in open-access papers:
TCP10L2 is named in the same sentence as 2 diseases in open-access papers, as found by Europe PMC text mining. Sharing a sentence is not in itself a finding about the gene and the disease. The quoted sentences say what the papers report.
lung carcinoma (1 paper, 2022). "Results showed that the signature based on MAS1L, TCP10L2, and CRHR2 is a useful tool to predict prognosis and lung cancer lymph node metastasis." (PMID 36277017, 2022).
tumour (1 paper, 2019). "The repression of ASB2 and TCP10L2 gene expression levels in HCC tumour mice treated with high-dose ascorbate compared to control was also verified." (PMID 31754384, 2019). "We validated the gene expression levels of AGER, DGKK, ASB2, TCP10L2, Lnc-ALCAM-3, and Lnc-TGFBR2-1 in HCC tumour tissue samples from mice treated with high-dose ascorbate by qPCR." (PMID 31754384, 2019).